OR10G3 (olfactory receptor family 10 subfamily G member 3)
Description:
Odorant receptor.
Synonyms: OR14-40
Tractability: Antibody: its Gene Ontology location is reachable by antibodies, with high confidence; UniProt places it where antibodies can reach, with medium confidence; UniProt predicts a signal peptide or a membrane-spanning region.
Gene: Protein-coding gene on chromosome 14 (21,568,520 to 21,580,076, reverse strand). Ensembl gene ENSG00000169208.
Subcellular location: Cell membrane
Pathways (Reactome):
Sensory Perception: Expression and translocation of olfactory receptors; Olfactory Signaling Pathway
Gene Ontology:
Molecular function: protein binding; olfactory receptor activity; G protein-coupled receptor activity
Biological process: detection of chemical stimulus involved in sensory perception of smell; G protein-coupled receptor signaling pathway
Cellular component: plasma membrane; membrane
Genetic constraint (gnomAD): Loss-of-function variants: 8 observed, 14.2 expected, observed/expected ratio (o/e) 0.56, 90% interval 0.33 to 1.02. The upper end of that interval is the gene's LOEUF score, 1.02, which puts it in group 4 of 6, group 1 being the genes least tolerant of losing a copy. Missense variants: 393 observed, 406.53 expected, observed/expected ratio (o/e) 0.97, 90% interval 0.89 to 1.05. Synonymous variants: 142 observed, 164.58 expected, observed/expected ratio (o/e) 0.86, 90% interval 0.75 to 0.99.
Homologues: Orthologues: chimpanzee OR10G3 (99% identical), pig OR10G3 (91% identical), mouse Or10g3 (87% identical), rabbit OR10G3 (87% identical), rat Or10g3 (86% identical), mouse Or10g3b (84% identical), rat Or10g3c (83% identical). Paralogues in human: OR10G2 (72% identical), OR10G6 (55% identical), OR10G4 (53% identical), OR10G9 (52% identical), OR10S1 (52% identical), OR10G7 (52% identical), OR10G8 (49% identical), OR10D3 (48% identical), OR2Y1 (42% identical), OR10A7 (41% identical), OR2B2 (41% identical), OR5V1 (41% identical), and 80 more.